NEFM (neurofilament medium chain)
Diseases named in the same sentence as NEFM in open-access papers (continued):
Sharing a sentence is not in itself a finding about the gene and the disease.
tumor (8 papers, 2008 to 2023). "Relationship of NEFM transcriptional expression with immunomodulators has implicated its involvement in regulating tumor immunology in BRCA." (PMID 34001208, 2021). "Firstly, macrophage markers IL6, CSF1R, CXCL12 were weak-to-strong positively associated with NEFM expression, which could reveal a potential role of NEFM transcriptional expression in regulating polarization of tumor-associated macrophage (TAM)." (PMID 34001208, 2021). "One potential mechanism by which NEFM methylation associated with poor survival may be NEFM methylation inducing tumor immunosuppression depending on decreased TILs." (PMID 34001208, 2021). "On the contrary, the overexpression of genes encoding muscle-like tumor antigens, such as NEFM, HSP60, and RYR3, may be a hallmark of thymic neoplastic tissue, which can predispose to MG in the presence of additional susceptibility molecular/genetic factors (e.g., susceptibility HLA alleles)." (PMID 36979710, 2023). "Comparing with normal tissues, higher levels of NEFM DNA methylation of NEFM were observed in tumors, while NEFM transcriptional expression was lower in tumor based on BRCA Illumina HiSeq RNA-Seq dataset including 1110 tumors versus 113 normal breast tissues." (PMID 34001208, 2021). "Our study highlights novel potential functions of NEFM expression/DNA methylation in regulation of tumor immune microenvironment." (PMID 34001208, 2021). "Five genes demonstrated complete loss or downregulation of expression in at least 20% of RCC tumours (GCM2 (80% of RCC), RGS7 (46.7%), TMEM74 (46.7%), NEFM (20%) and AEBP1 (20%))." (PMID 24034811, 2013). "Moreover, NEFM was positively associated with ectonucleotidases CD39 and CD73, novel checkpoint inhibitors that interfere with anti-tumor immune responses." (PMID 34001208, 2021). "Besides, NEFM transcriptional expression correlated with better prognosis and correlated with increased macrophage; after normalized with tumor purity, NEFM expression correlated with increased CD8+ T cell, whereas decreased B cell infiltration in BRCA." (PMID 34001208, 2021). "Thus, with subsequent investigation two candidate genes were found to be methylated in more than 25% of our series and in the TCGA methylation dataset for 199 RCC samples: RGS7 (25.6% and 35.2% of tumours respectively) and NEFM in (25.6% and 30.2%)." (PMID 24034811, 2013). "NEFM transcriptional expression was negatively associated with CCL7, CCL8 and CCL18, which would recruit monocytes to differentiate into tumor-associated macrophages (TAMs) at the tumor site, indicating that NEFM may cause decreased M2 macrophage infiltration." (PMID 34001208, 2021). "NEFM transcriptional expression was analyzed in BRCA and normal breast tissues using Oncomine and Tumor Immune Estimation Resource (TIMER) databases." (PMID 34001208, 2021). "Collectively, NEFM expression positively correlated with macrophage infiltration in TIMER and TISIDB; after adjusted with tumor purity, NEFM expression also weekly negatively correlated with infiltration level of B cell and positively correlated with CD8+ T cell in TIMER gene modules." (PMID 34001208, 2021). "NEFM, which was upregulated by a factor of 7.7 in the microarray analysis, was by IHC shown to be expressed only in the NE tumour cells group (data not shown)." (PMID 18827820, 2008). "Moreover, the relationship of NEFM transcriptional expression and NEFM DNA methylation with tumor-infiltrating immune cells was investigated in TCGA BRCA based on Tumor Immune Estimation Resource (TIMER) and TISIDB (tumor–immune system interactions)." (PMID 34001208, 2021).
neurodegenerative disease (7 papers, 2020 to 2025). A disorder of the central nervous system characterized by gradual and progressive loss of neural tissue and neurologic function. "The neurofilament polypeptides encoded by NEFH, NEFM, and NEFL are promising protein biomarkers for ALS and other degenerative diseases." (PMID 34511133, 2021). "Furthermore, as both NEFM, NPTXR, VGF and AQP4 have been implicated in other neurodegenerative disease in addition to FTD, it cannot be stated here that the profiles of the proteins included in the panel are specific for FTD." (PMID 34838088, 2021).
NEFM also shares sentences with these, for which no sentence is quoted: neurological diseases (7 papers); amyotrophic lateral sclerosis (6); Stroke (4); autism (2); frontotemporal dementia (2); multiple sclerosis (2); ovarian carcinoma (2); psychiatric disorder (2); schizophrenia (2); systemic lupus erythematosus (2); Ataxia (1); autoimmune disease (1); Autoimmunity (1); bipolar disorder (1); bladder carcinoma (1); bladder urothelial carcinoma (1); brain tumors (1); breast invasive carcinoma (1); carcinoid tumours (1); cervical cancer (1); cholangiocarcinoma (1); colon adenocarcinoma (1); colorectal cancer (1); dementia (1); diabetes (1); esophageal adenocarcinoma (1); graft versus host disease (1); head and neck carcinoma (1); head–neck squamous cell carcinoma (1); hereditary cerebellar ataxia (1).
A further 31 diseases each share a sentence with NEFM in 1 paper.